MYO1G (myosin IG)
Diseases named in the same sentence as MYO1G in open-access papers:
MYO1G is named in the same sentence as 27 diseases in open-access papers, as found by Europe PMC text mining. Sharing a sentence is not in itself a finding about the gene and the disease. The quoted sentences say what the papers report.
hepatocellular carcinoma (3 papers, 2020 to 2025). A malignant tumor that arises from hepatocytes. "Additionally, hypermethylation of MYO1G gene is a potential diagnostic biomarker for hepatocellular carcinoma." (PMID 40556672, 2025). "Our research is aimed at identifying and validating effective noninvasive biomarkers for HCC management, and our previously published study has indicated that hypermethylation of SCAND3 and Myo1g gene was a potential diagnostic biomarker for hepatocellular carcinoma." (PMID 33628341, 2021). "With regard to DNA methylation, the circulating tumor DNA methylation of MYO1G has been reported to be a promising biomarker for the diagnosis and disease monitoring of colorectal cancer and Hepatocellular Carcinoma." (PMID 40556672, 2025).
lung carcinoma (3 papers, 2019 to 2025). "After excluding MYO1G CpGs from Score-15, the positive association with lung cancer risk (10 of 13 CpGs available, OR = 1.15, 95% CI = 0.93–1.44) was attenuated relative to the association for the original Score-15." (PMID 39544416, 2024). "Excluding the CpGs in MYO1G eliminated the positive association of Score-15 and Score-19 with lung cancer risk, suggesting that prenatal-associated CpGs on MYO1G might have a notable association with lung cancer risk." (PMID 39544416, 2024). "Association between gene-level methylation scores (AHRR*, MYO1G, CYP1A1, FRMD4A, and GFI1*) and lung cancer risk, among ever smokers (186 matched pairs) nested in the CLUE II cohort (1989–2018)." (PMID 39544416, 2024). "While a role for MYO1G in lung carcinogenesis has not been established, we also identified concordant methylation of CpG sites in MYO1G associated with smoking in lung cancer and both newborn and adult blood." (PMID 30872662, 2019). "Since MYO1G is a member of the motor protein—class I myosin family and abundant in T and B lymphocytes and mast cells—it might indicate that prenatal smoking exposure might affect the mobility of leukocytes in the offspring’s lung cancer development." (PMID 39544416, 2024). "Similarly, in melanoma, lung cancer, and other diseases, we found that both CARD11 and MYO1G were underexpressed." (PMID 40386529, 2025).
acute lymphoblastic leukemia (2 papers, 2021 to 2022). Leukemia with an acute onset, characterized by the presence of lymphoblasts in the bone marrow and the peripheral blood. "In summary, this study illustrates that Myo1g expression might participate in the pathogenesis of the disease specially in high-risk patients of acute lymphoblastic leukemia and patients with translocation t(9:22)." (PMID 34548909, 2021). "Here, we report the development and application of new monoclonal antibodies against Myo1g for their potential use to detect its overexpression in acute lymphoblastic leukemia (ALL) patients." (PMID 35409272, 2022).
glioma (2 papers, 2025 to 2026). A benign or malignant brain and spinal cord tumor that arises from glial cells (astrocytes, oligodendrocytes, ependymal cells). "Methylation of the MGMT promoter is utilized as a biomarker to predict clinical response to a chemotherapeutic agent in glioma.With regard to MYO1G, cg10673833 located on MYO1G promoter region was reported to be a biomarker in the diagnosis and disease monitoring of colorectal cancer." (PMID 40556672, 2025).
melanoma (2 papers, 2025). A malignant, usually aggressive tumor composed of atypical, neoplastic melanocytes. "We linked the methylation levels of the two CpG sites with MYO1G expression and progression-free survival in our cohort of 104 melanoma patients treated with immunotherapy." (PMID 40556672, 2025). "In the independent melanoma cohorts receiving immune checkpoint blockade treatment, high MYO1G expression was significantly linked to improved clinical outcome." (PMID 40556672, 2025). "Our findings suggest that MYO1G promoter hypomethylation is associated with increased MYO1G expression and elevated immune infiltration in melanoma." (PMID 40556672, 2025). "We also found that high MYO1G mRNA expression level was significantly associated with prolonged progression-free survival among 53 melanoma patients treated with immunotherapy (P=0.04)." (PMID 40556672, 2025). "Subsequently, we associated MYO1G gene expression with overall survival in two independent cohorts including 94 immunotherapy-treated melanoma patients and 54 stage IV melanoma patients, respectively." (PMID 40556672, 2025). "Owing to the limited sample size, we were unable to observe a significant association between MYO1G promoter methylation and progression-free survival in melanoma patients receiving immunotherapy." (PMID 40556672, 2025). "Our findings demonstrated that promoter hypomethylation was significantly associated with increased gene expression of MYO1G, prolonged overall and progression free survival, and enhanced immune cell infiltration in melanoma." (PMID 40556672, 2025). "The prognostic value of MYO1G gene expression was robustly validated in 103 primary melanomas from TCGA and 54 stage IV melanomas from GSE22153." (PMID 40556672, 2025). "We investigated and corroborated the correlations of MYO1G DNA methylation with gene expression, and clinicopathologic parameters in 461 melanomas from The Cancer Genome Atlas (TCGA)." (PMID 40556672, 2025). "In particular, we plan to utilize in vivo melanoma models to investigate how MYO1G methylation status affects tumor progression and immune response in a physiological context." (PMID 40556672, 2025). "With regard to methylation, the melanoma patients were divided into high and low methylation group based on MYO1G promoter methylation level." (PMID 40556672, 2025). "Based on MYO1G promoter methylation defined by the mean methylation level of the 4 CpG sites, we also observed the melanoma patients belonging to low methylation group have longer overall survival (P=0.005) than those belonging to high methylation group." (PMID 40556672, 2025). "Then we robustly validated the correlations of promoter methylation with MYO1G gene in two cohorts including the 103 primary melanoma samples from TCGA and 104 advanced melanoma samples from this study." (PMID 40556672, 2025). "In conclusion, we first introduce the notion that MYO1G gene expression is regulated by promoter DNA methylation in melanoma." (PMID 40556672, 2025). "Our study highlights MYO1G promoter methylation as a key regulator of gene expression and a potential prognostic and predictive biomarker for immunotherapy response in melanoma." (PMID 40556672, 2025). "Our comparative analysis in the FAHZZU melanoma cohort showed that patients who responded well to immunotherapy had higher MYO1G expression levels, and those with elevated expression also exhibited longer progression-free survival." (PMID 40556672, 2025). "Further experimental validation, such as single-cell methylation or co-localization of MYO1G with exhausted T cell subsets in melanoma tissue, would help clarify this relationship." (PMID 40556672, 2025). "In contrast to promoter methylation, higher MYO1G gene expression can predict a better prognosis in melanoma." (PMID 40556672, 2025). "We further verified the prognostic value of MYO1G gene expression in a melanoma cohort treated with immunotherapy from Newell’s study." (PMID 40556672, 2025).
melanoma (continued). "It remains unknown that the effect of MYO1G DNA methylation on the gene expression, immune cell infiltration and immunotherapy response of melanoma." (PMID 40556672, 2025). "To investigate whether MYO1G expression is regulated by DNA methylation, we correlated the methylation levels of 9 CpG sites within the MYO1G gene with expression value among 358 melanoma samples from TCGA." (PMID 40556672, 2025). "We also validated that the MYO1G promoter hypomethylation could predict prolonged progress-free survival in primary melanoma." (PMID 40556672, 2025). "On the other hand, tumor purity defined as the percentage of cancer cells is negatively correlated with MYO1G expression, suggesting that a high expression level of MYO1G may promote anti-tumor immune response to suppress tumor cell proliferation in melanoma." (PMID 40556672, 2025). "However, the biological and clinical significance of MYO1G DNA methylation and gene expression in melanoma and its immune microenvironment remains unknown." (PMID 40556672, 2025). "While we demonstrated that MYO1G promoter hypomethylation may regulate gene expression and immune cell infiltration in melanoma patients based on multi-omics data from TCGA, it is important to acknowledge that these observations are derived from correlative bioinformatic analyses." (PMID 40556672, 2025). "However, how DNA methylation of MYO1G impacts its gene expression, tumor immune microenvironment, and clinical outcome of immunotherapy for melanoma patients remains unknown." (PMID 40556672, 2025). "However, the clinical significance of MYO1G promoter methylation in melanoma is still unknown." (PMID 40556672, 2025).
Cerebral cavernous malformation 2 (1 paper, 2020). "It localizes on mouse chromosome 11, in the intervening region of Myo1g (Myosin IG) and Ccm2 (Cerebral cavernous malformation 2) protein-coding genes, with well-defined gene structure and a binding peak of myogenic master transcription factor, MyoD on its promoter region." (PMID 32483152, 2020).
cutaneous melanoma (1 paper, 2025). A primary melanoma arising from atypical melanocytes in the skin. "Overall, our study confirmed that MYO1G promoter methylation and gene expression were predictive biomarkers for immune cell infiltration in the tumor microenvironment, prognosis and immunotherapy response of cutaneous melanoma patients." (PMID 40556672, 2025).
Hodgkins lymphoma (1 paper, 2022). A heterogeneous group of malignant lymphoid neoplasms of B-cell origin characterized histologically by the presence of Hodgkin and Reed-Sternberg (HRS) cells in the vast majority of cases. "MYO1G is abundant in T and B lymphocytes and mast cells, and CCR4 is a novel-specific molecular target for immunotherapy in Hodgkin lymphoma, able to regulate the cell trafficking of various leukocyte types." (PMID 35799269, 2022).
Immunodeficiency (1 paper, 2016). Failure of the immune system to protect the body adequately from infection, due to the absence or insufficiency of some component process or substance. "With respect to the immune response, up-regulated proteins (like FGA) were pro-inflammatory, while down-regulated proteins participated in antigen processing and antigen presenting (like MYO1G), immunoglobulin and cathelicidin production (like fowlicidin-2), and immunodeficiency (like PTPRC)." (PMID 27761697, 2016).
liver cirrhosis (1 paper, 2020). "Secondly, our study indicated that the serum Myo1g methylation frequency in HBV-related liver cirrhosis patients was 32.69%, which is higher than we observed in the BLD cases and HC." (PMID 32824823, 2020).
lung adenocarcinoma (1 paper, 2019). A carcinoma that arises from the lung and is characterized by the presence of malignant glandular epithelial cells. "In lung adenocarcinoma of current smokers, genome-wide significant CpGs annotated to multiple small nucleolar RNA genes, ribosomal subunit genes (RSPs), myosin immunoglobulin (MYO1G), and zinc finger protein 28 (ZFP28)." (PMID 30872662, 2019).
metastatic melanoma (1 paper, 2025). A melanoma that has spread from its primary site to another anatomic site. "Our study firstly identified significant inverse correlations of MYO1G gene expression with methylation level of 4 CpG sites including cg21188037, cg06787669, cg10673833 and cg22111043 in 358 metastatic melanoma samples, which were located on MYO1G promoter region." (PMID 40556672, 2025).
urogenital cancer (1 paper, 2016). "First, the DNA methylation and gene expression database MethHC shows that in urogenital cancer the methylation at 3’ gene region of MYO1G positively correlates with transcription, contrary to the promoter/5’UTR region methylation." (PMID 27171005, 2016).
viral infections (1 paper, 2021). "The absence of Myo1g decreases LFA-1 expression in B lymphocytes, suggesting that Myo1g could participate in the LFA-1-dependent IFN-γ production in the context of viral infections." (PMID 34970258, 2021). "The functional defects described by the absence of Myo1g and Myo1f could similarly affect NK cells, causing increased susceptibility to viral infections and tumor development." (PMID 34970258, 2021).
cancer (10 papers, 2012 to 2025). A tumor composed of atypical neoplastic, often pleomorphic cells that invade other tissues. "Myo1g has not previously been directly linked to cancer; although, other Class I myosins have gained interest in the field because some function as tumor suppressors, while others are overexpressed in different cancers." (PMID 35409272, 2022). "It should be noted that only SCAND3 methylation was found to be associated with early-stage HCC recurrence, and Myo1g has been not investigated previously in respect to human cancers." (PMID 32824823, 2020). "Besides AHRR, MYO1G, and CYP1A1, highlighted for having large effect sizes, several other genes implicated by CpGs overlapping between lung and blood are also cancer related." (PMID 30872662, 2019). "We evaluated the expression of Myo1g an hematopoietic restricted class I myosin that has not been studied in cancer before by qPCR, Immunofluorescence and ICQ at diagnosis, after complete remission and early in consolidation." (PMID 34548909, 2021). "In addition to the microtubule-interacting kinesins, we identified three actin-binding proteins, MYH1, MYO1G and TPM2, as essential proteins for cancer cell survival." (PMID 23071517, 2012). "In this study, we identified KIF11, KIF20A, KIF21, KIF25, MYO1G, MYH1 and TPM2 as proteins whose depletion causes growth inhibition and non-apoptotic cell death in cancer cells." (PMID 23071517, 2012). "Beyond our report of Myo1g overexpression in ALL, there are no other reports of the functional implications of Myo1g in cancer; however, such tools as our newly generated antibodies, here reported, could shed light on currently unknown functions of this family of unconventional myosins." (PMID 35409272, 2022).
tumor (8 papers, 2020 to 2025). "The associations of MYO1G gene expression and promoter hypomethylation with immune cell infiltrations and immune-related molecules reflect the impacts of MYO1G on anti-tumor immune response." (PMID 40556672, 2025). "In our cohort, patients with MYO1G promoter hypomethylation showed significantly elevated tumor-infiltrating lymphocytes level and prolonged progression-free survival after immunotherapy." (PMID 40556672, 2025). "Given that MHC class I serves as the receptor of HA-2, the interaction between RELT and MYO1G identified in our study suggests a potential mechanism by which tumor cells can evade immune recognition by CD8 + T cells upon cetuximab therapy." (PMID 38168324, 2023). "MYO1G gene expression was significantly and positively correlated with the expression of immune checkpoint genes (P < 0.001), suggesting that MYO1G promoter methylation regulated gene expression and subsequently impacted anti-tumor immune response." (PMID 40556672, 2025). "In summary, MYO1G promoter hypomethylation may regulate gene expression, then promote immune cell migration to tumors and intrigue anti-tumor immune response, resulting in improved prognosis of patients." (PMID 40556672, 2025). "TIMMER 2.0 web application analysis results indicated that increased MYO1G gene expression was inversely correlated with tumor purity, suggesting that MYO1G may play an important role in controlling tumor growth." (PMID 40556672, 2025). "Our study also provides new insight for understanding the biological significance of MYO1G expression and promoter methylation in lymphocytes infiltration into tumor, which may help turn immune-cold tumor to hot and enhancing immunotherapy response." (PMID 40556672, 2025). "In addition, the hypermethylation of Myo1g was significantly correlated with the tumor size (χ2 = 10.839, p = 0.001) and BCLC stage (χ2 = 10.277, p = 0.016)." (PMID 32824823, 2020). "One possible explanation is that elevated MYO1G expression in immune cells may participate in shaping the tumor immune landscape, potentially promoting T cell infiltration while simultaneously being involved in chronic stimulation and exhaustion signaling pathways." (PMID 40556672, 2025). "The other signature includes MYO1G that constitutes the minor histocompatibility antigen HA-2 that binds to MHC class I molecules, makes the antigens recognizable by CD8+T cells in tumor cells, and allows the destruction of harmful tumor cells." (PMID 39779996, 2025). "Interestingly, tumor resident ILC1 and NK cells also express Myo1g and Myo1f." (PMID 34970258, 2021).
cardiovascular diseases (1 paper, 2020). "Differential DNAm of CpGs linked to MYO1G gene may mediate the consequences of prenatal nicotine exposure such as increased leukocyte-endothelial adhesion (implicated in cardiovascular diseases) and immunologic abnormalities." (PMID 33419350, 2020).
MYO1G also shares sentences with these, for which no sentence is quoted: leukemia (2 papers); colorectal cancer (1); COVID-19 (1); developmental delay (1); Intellectual disability (1); nicotine dependence (1); Obesity (1); pulmonary tuberculosis (1); renal carcinoma (1); Sepsis (1).